PYGO2 (pygopus family PHD finger 2)
Diseases named in the same sentence as PYGO2 in open-access papers (continued):
Sharing a sentence is not in itself a finding about the gene and the disease.
tumor (continued). "Due to the importance of the role of the PYGO2 signaling pathway in tumorigenesis, our aim in this study was to compare PYGO2 protein expression in esophageal normal and tumor tissues and evaluate its possible correlations with ESCC progression." (PMID 40034933, 2024). "According to our observations, samples with tumor invasion (T3 & T4) showed a significantly higher expression of PYGO2 protein than other samples." (PMID 40034933, 2024). "Relationship between expression of PYGO2 protein in the ESCC tumor and normal tissue, clinicopathological characteristics and P-values." (PMID 40034933, 2024). "In this study, we found that the PYGO2 protein is significantly overexpressed in ESCC in correlation with the depth of tumor invasion." (PMID 40034933, 2024). "Previous studies have shown that abnormal expression of Pygo2 is related to tumorigenesis, chemoresistance, and tumor progression." (PMID 33854595, 2021). "Meanwhile, positive expression of Pygo2 was also related to lymph node metastasis (P = 0.025), increased tumour size (P = 0.041) and worse TNM stage (P = 0.037)." (PMID 31273950, 2019). "EGFR and PYGO2 mRNA expressions were assessed in tumor and corresponding normal margins in a sample of Iranian ESCC cases." (PMID 31470870, 2019). "Suppression of PYGO2 inhibited cell proliferation, colony formation, and tumor growth, suggesting that it promotes ovarian cancer progression." (PMID 31829231, 2019). "We have reported a significant correlation between MSI1 and PYGO2 and tumor depth of invasion in ESCC cases." (PMID 31470870, 2019). "In Pygo2 knock out mice, PYGO2 was clearly downregulated to undetectable levels in all tumor models." (PMID 27811361, 2016). "Although we did not see any apparent difference in tumor invasiveness or angiogenesis between controls and knockout animals, we suggest that Pygo2 is involved in tumor progression with respect to growth of the primary tumor." (PMID 27811361, 2016). "During the survival analyses of Ctnnb1 mutant mice, we observed that homozygous Pygo2 knockout animals survived the initial phase of tumor initiation for up to ten weeks after induction." (PMID 27811361, 2016). "In order to examine the potential role of Pygo2 expression on tumor cells invasion and metastasis, we established HCC cell lines by shRNA and plasmid construction methods in the present study." (PMID 25871475, 2015). "In the clinical HCC tumor samples, Pygo2 is also negatively correlated with the expression of E-cadherin." (PMID 25871475, 2015). "A significant reduction was observed in tumor size and mass of the Pygo2 shRNA tumors (n=5 for Pygo2 shRNA-1 and -2 groups) compared with those of the control shRNA tumors (n=5) (P=0.005)." (PMID 24348855, 2014). "Tumor weight of the two Pygo2 shRNA treated groups was significantly less than that of the control shRNA treated group (P<0.001)." (PMID 24348855, 2014). "To investigate the abnormalities of Pygo2 expression in NSCLC, we analyzed Pygo2 protein subcellular localization in 168 archived surgical tumor samples." (PMID 23865714, 2013). "We assessed Pygo2 expression in a semiquantitative manner based on the staining intensity and the percentage of tumor cells with nuclear staining." (PMID 23865714, 2013). "Overall, our data show that an abnormal Pygo2 expression profile correlates with tumor progression and poor prognosis in NSCLC." (PMID 23865714, 2013). "Regarding specific mechanisms, SPP1hi-TAMs can inhibit the anti-tumor function of CD8+ T cells through the adenosine-A2AR pathway; while Pygo2 inhibitors can reverse immune checkpoint inhibitor resistance by enhancing the infiltration of cytotoxic T lymphocytes in tumor tissues." (PMID 41488631, 2025). "However, it is unclear how molecular signatures such as PYGO2-negativity affect the tumor’s immunogenicity." (PMID 41133538, 2025). "Additionally, we analyzed the interactions between Pygo2+ CD8+ T cells and Pygo2- CD8+ T cells with tumor microenvironment cells." (PMID 40771810, 2025).
tumor (continued). "Previous studies associate PYGO2 with tumor stemness and invasiveness, yet our findings point to the possibility that PYGO2-negativity does not preclude aggressive behavior, especially in the presence of PI3K pathway activation." (PMID 41133538, 2025). "Tumor-infiltrating Pygo2+ T cells could be applied as a clinical prognosticator and a predictive biomarker for immunotherapy responsiveness to GC." (PMID 40771810, 2025). "Our investigation revealed that the majority of GC patients exhibited Pygo2 expression in their tumor cells, which might contribute to the restricted prognostic impact of Pygo2." (PMID 40771810, 2025). "Further investigation indicated that Pygo2 was predominantly expressed in T cells and tumor cells." (PMID 40771810, 2025). "Furthermore, we separately assessed the expression levels of Pygo2 in tumor cells, and T cells in GC and normal tissues." (PMID 40771810, 2025). "Previous research on the targets of Pygo2 has predominantly concentrated on tumor cells." (PMID 40771810, 2025). "A significant PYGO2 overexpression was observed in %32 of the tumor cells." (PMID 40034933, 2024). "Interestingly, PYGO2 expression was significantly correlated with the depth of tumor invasion (P= 0.021)." (PMID 40034933, 2024). "Furthermore, in line with a previous report on glioma cancer, the rate of tumor grade increased with PYGO2 overexpression, and a positive correlation between PYGO2 expression and tumor grade was observed." (PMID 40034933, 2024). "Notably, PYGO2, UBQLN4, and ANXA1 have been associated with responsiveness to tumor immune checkpoint blockade (ICB) therapy, while B4GAL and MDM2 are implicated in regulating CD8 + T cell function and tumor growth." (PMID 38834869, 2024). "EGFR/PYGO2 overexpression had significant correlations with surgical stage and tumor grade." (PMID 31470870, 2019). "Most importantly, Pygo2 deletion significantly reduced tumor number and size." (PMID 27811361, 2016). "PYGO2 was strongly expressed in the nuclei of the tumor cells in controls, but not detectable in tumors of Pygo2 deficient mice." (PMID 27811361, 2016). "This might explain why Pygo2 knockout cannot prevent tumorigenesis, but reduces tumor formation in vivo." (PMID 27811361, 2016). "Knockdown of Pygo2 significant increased E-cadherin protein level in transplanted tumor tissue." (PMID 25871475, 2015). "There was a strong correlation between Pygo2 overexpression and tumor stage." (PMID 23865714, 2013). "Thus, targeting Pygo2 might provide a novel strategy to suppress tumor formation in a context dependent manner." (PMID 27811361, 2016). "Moreover, deletion of Pygo2 cannot rescue the overexpression of c-Myc in this tumor model." (PMID 27811361, 2016). "Multiple studies have confirmed that PYGO2 is highly expressed at both mRNA and protein levels in HCC tissues, implicating its role in tumor progression, particularly through the promotion of cell migration." (PMID 41133538, 2025). "Metastatic Potential: Overexpression of PYGO2 or dysregulation of its regulatory regions can promote epithelial-to-mesenchymal transition (EMT), facilitating tumor metastasis and dissemination to distant organs." (PMID 41133538, 2025). "Consequently, Pygo2+ T cells may serve as a potential biomarker of tumor immunotherapy efficacy." (PMID 40771810, 2025). "Select genes including ALDH3B1, CEACAM5, IL8, PYGO2, and WWTR1, exhibited pronounced activity in promoting tumor formation and establishing gene dependencies critical for tumorigenicity." (PMID 38851782, 2024). "In another study, hsa-miR-432 has been shown to act as a tumor suppressor gene by targeting LRP6, TRIM29, and Pygo2, thus deactivating the Wnt pathway." (PMID 38326829, 2024). "Expression levels of PYGO2, KDM5B, PHF20L1, and ZMYND8 were also significantly higher in tumor samples compared to that in non-tumor breast tissue." (PMID 28055972, 2017).
tumor (continued). "Knocking down Pygo2 expression in these cells not only inhibited proliferation in vitro (demonstrated by MTS and colony formation assays), but also suppressed tumor growth in vivo." (PMID 24348855, 2014). "Additional analyses indicated that Pygo2 expression in tumor cells did not demonstrate a significant correlation with patient survival." (PMID 40771810, 2025). "Further examination demonstrated that the expression of Pygo2 in overall cells and tumor cells did not significant correlation with patient survival." (PMID 40771810, 2025). "The results showed that the expression of Pygo2 in tumor cells, and T cells were both higher in GC, compared with normal gastric tissues." (PMID 40771810, 2025). "The findings indicated that there were no significant clinical pathological differences in Pygo2 expression between the overall cells and tumor cells." (PMID 40771810, 2025). "High expression of PYGO2, the pivotal transcription factor of wingless-type mouse mammary tumor virus integration site (WNT) signaling pathway, was detected in ESCC in correlation with tumor invasion and advanced stages of the disease." (PMID 37205315, 2023). "In another study we have also shown that there wre significant correlations between MAML1 and PYGO2 as the main components of NOTCH and WNT signaling transcriptional machineries respectively and tumor depth of invasion and size among a group of Iranian ESCC cases." (PMID 31470870, 2019). "Conditional deletion of Pygo2 in MMTV-Wnt1 animals similarly delayed the tumor onset, indicating that Pygo2 also enhances Wnt1 driven tumorigenesis, remarkably without affecting the Wnt/ß-catenin signaling output." (PMID 25149534, 2014). "When PYGO2 is negative in HCC, it suggests that the gene may not be expressed or that the protein it encodes is not functioning as expected in the tumor cells." (PMID 41133538, 2025). "The negative PYGO2 status does not necessarily indicate poor prognosis directly, but it suggests that the tumor may not benefit from therapies targeting the Wnt/β-catenin pathway." (PMID 41133538, 2025). "Tumors that lack PYGO2 may not show the same types of tissue remodeling or regenerative features driven by the Wnt/β-catenin pathway, which could make the tumor behave differently from others that are Wnt-positive." (PMID 41133538, 2025). "Indeed, 28 out of the 37 (75.67%) invasive tumor samples (T3, T4) showed overexpression of PYGO2 protein, whereas 13 tumor samples without invasion to adventitia (T2) showed PYGO2 overexpression." (PMID 40034933, 2024). "In contrast, Pygo2 ablation was not sufficient to prevent tumor development of Apc LOF mice." (PMID 27811361, 2016). "However, whether or not PYGO2 exerts these tumor-promoting effects by promoting β-catenin/TCF activity requires further confirmation." (PMID 31829231, 2019). "In this particular case of PIK3CA-positive and PYGO2-negative HCC, we should expect an aggressive tumor with PI3K pathway activation." (PMID 41133538, 2025). "To our knowledge, the immunophenotype combining PIK3CA-positive and PYGO2-negative staining in HCC is rarely documented; we therefore report this case and discuss its implications for tumor biology and therapy." (PMID 41133538, 2025).
cancer (17 papers, 2010 to 2025). A tumor composed of atypical neoplastic, often pleomorphic cells that invade other tissues. "Molecular Pathways: The loss of PYGO2 may influence various signaling pathways involved in cell adhesion, migration, and survival, which are critical in cancer progression and metastasis." (PMID 41133538, 2025). "Pygo2 has been implicated in Wnt-independent roles in both cancer and development." (PMID 23865714, 2013). "This discovery not only elucidates the tripartite nexus among Pygo2 expression, T cell exhaustion, and tumorigenesis but also offers a new biological target for cancer immunotherapy." (PMID 40771810, 2025). "Given the well-established role of Wnt/β-catenin dysregulation in the development and progression of various malignancies, it is reasonable to infer that PYGO2 also plays a significant role in tumorigenesis and cancer progression." (PMID 41133538, 2025). "Repression of PYGO2 inhibited cancer development, aggression, and epithelial-mesenchymal transition (EMT)." (PMID 40034933, 2024). "Pygo2 is overexpressed in various cancers, including colorectal, breast, lung and prostate cancer, and its overexpression is linked to poor prognosis." (PMID 37349336, 2023). "Inhibition of Pygo2 expression in cancer cells suppresses their proliferation and invasiveness and decreases the expression of Wnt target genes." (PMID 37349336, 2023). "Pygo2 is usually maintained at a low level in normal cells but has shown an abnormally high expression level in some cancers." (PMID 33854595, 2021). "This study also provided a potential therapeutic target in the treatment of cancers where Pygo2 is overexpressed." (PMID 33854595, 2021). "As expected, we found that BCL9-2 consistently co-precipitated with Pygo2 in all analyzed cancer cells." (PMID 25149534, 2014). "Of the two Pygo paralogs, Pygo2 appears to be the more functionally relevant, both in normal development and in cancer." (PMID 20637214, 2010). "Furthermore, the article offers preliminary insights into the potential interactions between Pygo2 and T cells, thereby providing new avenues for future cancer treatment strategies." (PMID 40771810, 2025). "Since PYGO2 plays a vital role in cancer progression and development through the wnt signaling pathway, it can be suggested as a probable therapeutic target to inhibit and reverse cancer invasiveness." (PMID 40034933, 2024). "It is believed that PYGO2 may play a vital role in cancer progression; therefore, it can be used as a therapeutic target for cancer therapy." (PMID 40034933, 2024). "Pygo2 overexpression has been identified in several cancers." (PMID 33854595, 2021). "Pygo2 may be a novel biomarker for monitoring drug resistance and a potential therapeutic target for cancer treatment in the future." (PMID 33854595, 2021). "However, since this drug apparently has also toxic effects, further compounds have to be developed and tested in vivo to target Pygo2 for the treatment of cancers with mutant ß-catenin." (PMID 27811361, 2016). "We hypothesize that increased Pygo2 protein expression may serve as a marker of advanced NSCLC, although additional work is needed to identify the specific mechanisms of Pygo2-mediated cancer progression." (PMID 23865714, 2013). "Therefore, cancers driven by Wnt hyperactivity or Pygo2 overexpression may rely substantially on the Pygo-ChiLS-containing core complex of the Wnt enhanceosome for the transcriptional activity of cancer-relevant Wnt target genes." (PMID 37349336, 2023). "In addition, Pygo2 over-expression has been reported in ovarian, breast, cervical and lung cancers." (PMID 25871475, 2015). "Moreover, Pygopus 2 (Pygo2) is another canonical Wnt co-activator, which binds to trimethylated H3K4 loci to promote cancer progression and dedifferentiation." (PMID 37792222, 2024).
cancer (continued). "In the present study, we applied shRNA-mediated Pygo2 depletion technology to down-regulate endogenic Pygo2 in MHCC-97H cells and demonstrated for the first time that weaken Pygo2 expression can inhibited the invasion of live cancer cells and metastasis in vitro." (PMID 25871475, 2015).
PYGO2 also shares sentences with these, for which no sentence is quoted: esophageal squamous cell carcinoma (2 papers); astrocytoma (1); bladder cancer (1); congenital heart defects (1); diffuse astrocytoma (1); enteritis (1); esophageal cancer (1); liver fibrosis (1); lymph node metastasis (1); malignant glioma (1); mandibulofacial dysostosis (1); metastatic colorectal cancer (1); microtia (1); renal cell carcinoma (1); Septo-optic dysplasia (1); triple-negative breast carcinoma (1).